ZNHIT2 (zinc finger HIT-type containing 2)
Description:
May act as a bridging factor mediating the interaction between the R2TP/Prefoldin-like (R2TP/PFDL) complex and U5 small nuclear ribonucleoprotein (U5 snRNP). Required for the interaction of R2TP complex subunit RPAP3 and prefoldin-like subunit URI1 with U5 snRNP proteins EFTUD2 and PRPF8. May play a role in regulating the composition of the U5 snRNP complex.
Synonyms: C11orf5; FON
Tractability: PROTAC: ubiquitination databases record sites on it; its protein half-life has been measured.
Gene: Protein-coding gene on chromosome 11 (65,116,403 to 65,117,701, reverse strand). Ensembl gene ENSG00000174276.
Gene Ontology:
Molecular function: protein binding
Genetic constraint (gnomAD): Loss-of-function variants: 26 observed, 19.95 expected, observed/expected ratio (o/e) 1.3, 90% interval 0.95 to 1.77. The synonymous counts are far from expectation, so gnomAD's model fits this gene poorly and the ratio says little. Missense variants: 631 observed, 476.14 expected, observed/expected ratio (o/e) 1.33, 90% interval 1.24 to 1.41. Synonymous variants: 336 observed, 232.83 expected, observed/expected ratio (o/e) 1.44, 90% interval 1.32 to 1.58.
Homologues: Orthologues: chimpanzee ZNHIT2 (99% identical), macaque ZNHIT2 (92% identical), pig ZNHIT2 (87% identical), mouse Znhit2 (82% identical), dog ZNHIT2 (82% identical), guinea pig ZNHIT2 (80% identical), rat Znhit2 (75% identical), tropical clawed frog znhit2 (37% identical), zebrafish znhit2 (31% identical), Drosophila melanogaster CG31223 (20% identical), Caenorhabditis elegans zhit-2 (11% identical).
Diseases named in the same sentence as ZNHIT2 in open-access papers:
ZNHIT2 is named in the same sentence as 3 diseases in open-access papers, as found by Europe PMC text mining. Sharing a sentence is not in itself a finding about the gene and the disease. The quoted sentences say what the papers report.
endometriosis (1 paper, 2020). The growth of functional endometrial tissue in anatomic sites outside the uterine body. "Therefore, altered ZNHIT2 levels seen in endometriosis may dysregulate alternative splicing of hTERT which is often found in cancers." (PMID 33317189, 2020).
thyroid cancer (1 paper, 2023). "Compared with normal thyroid tissue, 7 CRGs were more highly expressed in thyroid cancer, namely BUB1 (P<0.001), RPL3 (P<0.001), TTK (P<0.001), GINS2 (P<0.001), SLC26A6 (P<0.001), CDKN2A (P<0.001) and ZNHIT2 (P<0.001)." (PMID 37745716, 2023).
ZNHIT2 also shares sentences with these, for which no sentence is quoted: cancer (1 paper).